SIRT1 (sirtuin 1)
Diseases named in the same sentence as SIRT1 in open-access papers (continued):
Sharing a sentence is not in itself a finding about the gene and the disease.
Hepatic steatosis (continued). "Progression in fatty liver disease could be stopped by the AMPKa2-SIRT1-PPAR-α signaling pathway and by the SIRT1-mediated NLRP3 inflammasome suppression." (PMID 35956321, 2022). "The deacetylation effect of SIRT1 on histone was reported to improve hepatic steatosis." (PMID 34572442, 2021). "For example, neural deletion of SIRT1 improves insulin sensitivity and glucose intolerance in mice, while the administration of the pharmacological inhibitor EX-527 improves body weight, food intake, hepatic steatosis and fibrosis in diabetic rats." (PMID 33572672, 2021). "As a natural activator of SIRT1, resveratrol has been reported to prevent hepatic steatosis and even ameliorate fibrosis, and it could also improve ethanol-induced insulin resistance and regulate ethanol metabolism enzymes." (PMID 33728021, 2021). "Furthermore, mIR-34a levels correlate with lipid accumulation and increase hepatic steatosis through reduced fatty acid oxidation and increased mitochondrial damage by targeting SIRT1." (PMID 33806509, 2021). "In mammals, studies showed that low levels of serum SIRT1 were observed in obese patients with liver steatosis, and liver-specific SIRT1-knockout mice showed hepatic lipid accumulation, suggesting that SIRT1 was a negative modulator of the SREBP-1 lipogenic pathway." (PMID 34248992, 2021). "In support to these findings, hepatocyte-specific deletion of Sirt1 resulted in hepatic steatosis and inflammation, whereas both transgenic SIRT1 mice and overexpression of SIRT1 specifically in the liver showed lower hepatic steatosis along with better glucose tolerance." (PMID 34572442, 2021). "In addition, inhibition of PARP-1 can also increase NAD+ content and SIRT1 activity, enhance lipid metabolism, and improve hepatic steatosis in mice fed a high-fat diet." (PMID 34393826, 2021). "Overall, the present study revealed that dietary betaine supplementation alleviated hepatic steatosis-induced inflammation through Sirt1/Pparɑ signaling pathway-mediated suppression of NF-kB and, consequently, attenuated NF-kB driven inflammation response in black seabream." (PMID 34248992, 2021). "The metformin-improved hepatic steatosis in Sirt1+/− mice may have an indirect effect on reducing hepatic inflammation." (PMID 34483906, 2021). "The Sirt1/AMPK pathway can participate in hepatic steatosis in obese mice." (PMID 34054544, 2021). "NAC could also preserve the expression level of PGC1a and SirT1, which further supports the role of SirT1/PGC1a in the treating effect of NAC in dealing with hepatic steatosis." (PMID 34588976, 2021). "Activated Sirt1 could promote AMPK phosphorylation, and it also can be regulated by phosphorylation AMPK on the contrary, while loss of Sirt1 could increase hepatic steatosis and inflammation in mice." (PMID 34690775, 2021). "This is the first report to suggest that dietary betaine could be an effective feed additive to alleviate hepatic steatosis and attenuate inflammatory responses in black seabream fed a high fat diet by modulating the Sirt1/Srebp-1/Pparɑ pathway." (PMID 34248992, 2021). "Moreover, metformin reduced liver weight without changing the liver weight to body weight ratio and ameliorated the hepatic steatosis in Sirt1+/− mice." (PMID 34483906, 2021). "Metformin was shown to alleviate fatty liver through increasing SIRT1-mediated autophagy." (PMID 33806509, 2021). "In addition, miR‐34a has been shown to contribute to hepatic steatosis by inhibiting sirtuin 1 (Sirt1)." (PMID 33159388, 2021). "It has been reported that hepatocyte-specific deletion of Sirt1 aggravated hepatic steatosis." (PMID 34803499, 2021). "Li and his colleagues also found that Pleurotus citrinopileatus aqueous extract inhibits inflammation by regulating SIRT1-AMPK sum to improve alcoholic hepatic steatosis and inhibit the activation of P2X7R-NLRP3 inflammatory bodies, thus achieve the purpose of treating alcoholic fatty liver." (PMID 35002763, 2021).
Hepatic steatosis (continued). "In the liver, Sirt1 plays a beneficial role in regulating lipid metabolism and controlling oxidative stress and inflammation by deacetylating some transcriptional regulators against the progression of fatty liver disease." (PMID 34575829, 2021). "SIRT1 is one of the important genes identified in the pathogenesis of fatty liver disease." (PMID 34988225, 2021). "In addition, mounting evidence indicates that a long-term, high-calorie-diet induced liver steatosis is promoted by increasing the expression of SIRT1 in animals." (PMID 32230804, 2020). "BBR has also been shown to attenuate hepatic steatosis in a SIRT1-dependent manner." (PMID 33390968, 2020). "However, the better efficacy in improving hepatic steatosis by exercise in the GCN2-deficient mice enhanced liver lipid metabolism, at least partially, via the AMPK/SIRT1/PPARα pathway." (PMID 33299856, 2020). "Whether the higher levels of SIRT1 and adiponectin found in AN may be protective against more severe forms of liver steatosis deserves further investigation." (PMID 33202604, 2020). "However, in this state, the biological effect of glucagon is weakened, and the impact of glucagon on SIRT1 is also impaired, while SIRT1 can inhibit hepatic steatosis and inflammatory responses to hepatic metabolic disorders." (PMID 30995792, 2019). "Moreover, the beneficial effects of SLBZS on hepatic steatosis, some biochemical parameters and hepatic lipid species were partly diminished by SIRT1 inhibition." (PMID 31683679, 2019). "Thus, hepatic overexpression of NAMPT restores NAD+ levels, and thereby alleviates ethanol-induced hepatic steatosis in a SIRT1-dependent manner." (PMID 30794635, 2019). "GC supplementation in overweight or obese NAFLD patients showed a significant beneficial effect on the grade of fatty liver, serum glucose indices, and lipid profiles, which may be mediated by an increase in serum Sirt1 and irisin concentration." (PMID 30871514, 2019). "SIRT1-knockout mice showed lower fatty acid oxidation and higher hepatic steatosis." (PMID 30832407, 2019). "We hypothesized that moderate intensity aerobic exercise training delays the progression of diabetic nephropathy and hepatic steatosis by restoring SIRT1-mediated metabolic and inflammatory signaling in db/db mice, a model of T2DM." (PMID 30988688, 2019). "Thus, it has been proposed that the Nampt/NAD/SIRT1 axis can suppress hepatic steatosis in HFD-fed mice." (PMID 31078136, 2019). "Based on these results, CT-mediated-AMPK/SIRT1 activation might play a critical role in the protective effects of CT against alcoholic fatty liver." (PMID 31906014, 2019). "These evidences prompted us to study whether SIRT1 mediated the effects of NAMPT on ethanol-induced liver steatosis." (PMID 30794635, 2019). "Conversely, SIRT1 overexpression restores the diet-induced hepatic steatosis." (PMID 31078136, 2019). "Furthermore, α-MG decreased hepatic steatosis through the hepatic SirT1-AMPK and PPAPγ pathways in obese mice." (PMID 30959963, 2019). "The effect of SIRT1 on integration of metabolism and inflammation may provide a therapeutic target for treatment of kidney disease and fatty liver disease." (PMID 30988688, 2019). "In addition, miR-34a regulates AMPKα activity through mediating SIRT1 pathway to suppress the development of fatty liver." (PMID 29681936, 2018). "However, co-treatment with Ex52735 significantly blocked the GN-mediated reduction in TG accumulation, suggesting that GN-induced protection against ethanol-induced hepatic steatosis is mediated by SIRT1 up-regulation." (PMID 30200508, 2018). "In addition, miR-34a inhibition increases the levels of phosphorylated AMPKα separately through mediating PPARα regulation and SIRT1 pathway to suppress the development of fatty liver." (PMID 29681936, 2018). "Therefore, the three flavonones from P. chinense were found to exert preventive effects against hepatic steatosis by regulating the SIRT1/AMPK pathway." (PMID 30154382, 2018).
Hepatic steatosis (continued). "Thus, we suggested that both AMPK and SIRT-1 activation mediated by MGF was involved in its anti-hepatic steatosis effect." (PMID 29563875, 2018). "Inhibition of AMPK or SIRT1 pathway thus blocked the beneficial effects of Rb2, suggesting that the effect of Rb2 on alleviating hepatic steatosis may be achieved through autophagy induction." (PMID 30618753, 2018). "Administrate resveratrol (200 mg/kg bodyweight) to rats under high fat diet conditions significantly prevented hepatic steatosis and hepatocyte ballooning after 18-week treatment, along with the up-regulation of SIRT1 and autophagy markers LC3-II, Beclin 1, and P62." (PMID 30618753, 2018). "In the present study, males had a reduction in both Sirt1 and PPARα, which is indicative of the mechanism through which lipid accumulation occurs in the liver, and that may contribute to the genesis of hepatic steatosis." (PMID 30304827, 2018). "Taken together, these results suggest that the SIRT1-AMPK pathway might play a critical role in the protection of GN against ethanol-induced hepatic steatosis." (PMID 30200508, 2018). "SIRT1 was inversely associated with EFT, total FM%, liver steatosis, body weight, BMI, and WC." (PMID 30131769, 2018). "Sirt1 has a beneficial effect by regulating hepatic lipid metabolism, controlling hepatic oxidative stress, and hepatic inflammation through deacetylating transcriptional regulators against the progression of fatty liver disease." (PMID 30055626, 2018). "Overexpression of SIRT1 in mice attenuates hepatic steatosis and improves insulin sensitivity." (PMID 28904866, 2017). "In another diet-induced mouse model of early hepatic steatosis Sirt1 activity was increased." (PMID 28207798, 2017). "Furthermore, previous studies showed that modest overexpression of SIRT1 led to a protective effect on high-fat induced glucose intolerance and hepatic steatosis." (PMID 29123480, 2017). "Notably, direct or indirect evidences obtained from a cell-free system, HepG2 cells, and a hepatic steatosis the mouse model consistently supports the notion that scopolin can act as an activator of SIRT1 deacetylation." (PMID 28533555, 2017). "We found that resveratrol (200 mg/kg bw) and caloric restriction (30%) partially prevented hepatic steatosis and hepatocyte ballooning, increased the expression of SIRT1 and autophagy markers while decreasing ER stress markers in the liver and alleviated lipid metabolism disorder." (PMID 28817690, 2017). "However, the mechanism by which SIRT1 regulates hepatic PPARγ function, especially in alcoholic fatty liver, remains poorly understood." (PMID 27404390, 2016). "Hepatic induction of FGF21 by SIRT1 has been shown to protect from liver steatosis." (PMID 27669233, 2016). "Accordingly, SIRT1 transgenic mice exhibited a low level of acetylated PPARγ and were protected from hepatic steatosis driven by alcohol or PPARγ2 overexpression, suggesting that ethanol metabolism causes lipid accumulation through activation of PPARγ through acetylation." (PMID 27404390, 2016). "Moreover, RSV is a well-known activator of SIRT1 and our previous study also found that RSV improved hepatic steatosis partially by inducing autophagy via the SIRT1 signaling pathway in vitro and in vivo (36, –, 38)." (PMID 27048804, 2016). "In addition, ASP markedly alleviated serum and liver lipid disorders and fatty liver via the upregulation of PPARγ expression and the activation of adiponectin-SIRT1-AMPK signaling." (PMID 27189109, 2016). "Moreover, leucine synergizes with PDE5 inhibitors to exert amplifying downstream effects of AMPK and Sirt1 activation on glucose and fat metabolism as well as reversal of hepatic steatosis and inflammation in vitro and in vivo." (PMID 28042486, 2016).
Hepatic steatosis (continued). "Conversely, low-level SIRT1 overexpression promotes glucose tolerance, insulin sensitivity, and prevents fatty liver disease, highlighting the beneficial effects of SIRT1 action and supporting the proposal that SIRT1 activation could be of therapeutic value." (PMID 27058248, 2016). "In contrast, even moderate SIRT1 overexpression in mice could protect against the development of hyperglycemia, fatty liver, and metabolic diseases." (PMID 24759758, 2014). "Hepatocyte-specific SIRT1-deleted mice challenged with a high-fat diet developed hepatic inflammation and hepatic steatosis, and SIRT1-null mice were shown to accumulate deposits of immune complexes in the liver and kidney and develop an autoimmune-like condition." (PMID 24498364, 2014). "Additionally, Sirt1 overexpression in mice protects against hepatic steatosis induced through a high-fat diet." (PMID 25133775, 2014). "We observed a significant increase of HSP72, PPARα and Sirt1 with amelioration of hepatic steatosis, particularly in the combined treatment group, suggesting that not only vildagliptin, but also valsartan may participate in activating this pathway." (PMID 24188631, 2013). "The protective action of carvacrol against HFD-induced hepatic steatosis in mice appears to be mediated through the downregulation of genes involved in lipogenesis and upregulation of genes involved in fatty acid oxidation via SIRT1-AMPK signaling." (PMID 23533470, 2013). "Other studies show that SIRT1 decreases histone H3 at Lys-9 in ethanol-induced fatty liver in mice." (PMID 23825667, 2013). "A novel finding of this study was the observation that expression of GLP-1R is proportional to exendin-4 concentration and exendin-4 could attenuate fatty liver through activation of Sirt1." (PMID 22363635, 2012). "Additionally, recent studies demonstrated that modest overexpression of Sirt1 resulted in a protective effect against high fat induced hepatic steatosis and glucose intolerance." (PMID 21549004, 2011). "Sirt1 and Sirt6 also both show protective effects against hepatic steatosis." (PMID 21373642, 2011). "In light of previous findings, our data demonstrating the involvement of Sirt6 in the RGZ-mediated protection of hepatic steatosis suggest that Sirt6 may have functional similarities with Sirt1 as a metabolic regulator." (PMID 21373642, 2011). "Indeed, rmSIRT1 reduced both hepatic steatosis and atherosclerotic phenotype in the ApoE−/− mice, therefore our study might be a first step towards establishing circulating SIRT1 as a potent therapeutic against the global lipid burden." (PMID 40653676, 2025). "Since hepatic VLDLR levels are elevated in response to ER stress and as they contribute to ER stress-dependent hepatic steatosis, we next evaluated whether SIRT1 activation attenuated VLDLR upregulation and the hepatic steatosis caused by the ER stressor tunicamycin." (PMID 38807218, 2024). "Furthermore, SIRT1 ameliorates hepatic steatosis through the activation." (PMID 38543036, 2024). "In addition, SIRT1 could also inhibit NF-κB activity to reduce the inflammatory response, which is a powerful defender against pathologic conditions like fatty liver." (PMID 37834101, 2023). "Sirtuin-1 may also exert a protective role against hepatic steatosis." (PMID 36139771, 2022). "Furthermore, liver steatosis associated with a high-fat KD was not accompanied by modulation in intrahepatic SIRT1." (PMID 36555502, 2022). "Therefore, we tested the requirements of SIRT1 in PLZF-induced hepatic steatosis in vivo." (PMID 36438786, 2022). "Strategies to activate both KBs and SIRT1 could be used to treat fatty liver disease." (PMID 35956321, 2022). "Hence, our data suggested that Grail-mediated regulation of Sirt1 level and activity might play an important role in the progression of hepatic steatosis." (PMID 33771967, 2021).
Hepatic steatosis (continued). "Together, our data suggested that Sirt1 plays a vital role in activating HPCs to repair fatty liver injury or promote liver regeneration through the Wnt/β-catenin signal pathway in NAFLD, which might provide a new strategy for fatty liver injury or NAFLD therapy." (PMID 34977130, 2021). "The presented data suggest that during experiment conditions the observed liver steatosis was not followed by the changes on the expression level of genes encoding the AMPK or SIRT1 proteins, which are known as the major regulators of cellular lipid and glucose metabolism." (PMID 34836410, 2021). "However, whether the effect of metformin on improving hepatic steatosis depends on SIRT1 remains unclear." (PMID 34483906, 2021). "Furthermore, our findings revealed that dietary betaine supplementation alleviated hepatic steatosis-induced inflammation through Sirt1/PPARɑ signaling pathway mediated suppression of NF-kB and, consequently, attenuated NF-kB driven inflammation response in black seabream." (PMID 34248992, 2021). "Moreover, deletion of Sirt1 impaired liver regeneration, as evidenced by a decreased liver-to-body weight ratio, reduced indices of hepatocyte proliferation, and lead to hepatic steatosis as reflected in histology and hepatic triglyceride content." (PMID 33690226, 2021). "Further, autophagy may be mediated directly by the AMPK/SIRT1 pathway in hepatic steatosis." (PMID 34095107, 2021). "However, whether SIRT1 is indispensable for the effect of metformin on improving hepatic steatosis and inflammation remains unclear." (PMID 34483906, 2021). "However, the hepatitis was not improved at all by metformin in Sirt1+/− mice, which indicates that SIRT1 deficiency promotes steatohepatitis and this effect is independent of the improved hepatic steatosis." (PMID 34483906, 2021). "Importantly, the present study indicates a possible mechanism whereby the combination of GCN2 deficiency and exercise may suppress the initiation of HFD-induced hepatic steatosis more effectively by activation of the AMPK/SIRT1/PPARα pathway in the liver." (PMID 33299856, 2020). "Furthermore, SIRT1 was shown to be protectiveagainst hepatic steatosis." (PMID 32779442, 2020). "However, the protective effect of SIRT1 inhibitor in hepatic steatosis and fibrosis and its underlying mechanism is not clearly understood." (PMID 32365537, 2020). "Hence, SIRT1 may represent a novel therapeutic target for the treatment of the fatty liver disease in dairy cows." (PMID 32230804, 2020). "Hence, SIRT1 may represent a novel therapeutic target for the treatment of fatty liver disease in dairy cows." (PMID 32230804, 2020). "In addition, our other study preliminarily indicated that SLBZS could improve hepatic steatosis and activate Sirtuin 1 (SIRT1) in the liver." (PMID 31683679, 2019). "Notably, the overexpression of Sirt1 via AAV9-Sirt1 alleviated liver steatosis in the AFLD mice." (PMID 31076642, 2019). "Since SIRT1 has been shown to regulate ethanol-induced liver steatosis, we hypothesized that increased NAD+ production and SIRT1 activity caused by NAMPT overexpression contributed to the alleviation of ethanol-induced hepatic steatosis." (PMID 30794635, 2019). "Moreover, Sirt1 mediates the protection of a GLP-1R agonist on HFD-induced hepatic steatosis." (PMID 30533173, 2018). "Therefore, suppressing in hepatic steatosis may attribute to APS1-induced butyrate expression triggering hepatic protective functions of SIRT1." (PMID 29670255, 2018). "However, it is still unknown whether resveratrol, by mimicking the effects of caloric restriction prevents hepatic steatosis by regulating the SIRT1-autophagy pathway and alleviates ER stress." (PMID 28817690, 2017). "Consequently, the lower abundance of SIRT1 in high-FE animals might lead to reduced hepatic fatty acid oxidation compared to low-FE pigs, and eventually results in the development of hepatic steatosis under high-fat diets." (PMID 28763040, 2017).